GSDMB (gasdermin B)
Diseases named in the same sentence as GSDMB in open-access papers (continued):
Sharing a sentence is not in itself a finding about the gene and the disease.
breast carcinoma (continued). "Here, using an in silico analysis of data from 2,096 breast tumours, we reveal a significant correlation between Gasdermin B (GSDMB) gene (located 175 kilo bases distal from ERBB2) expression and the pathological and clinical parameters of poor prognosis in HER2-positive breast cancer." (PMID 27462779, 2016). "We have previously reported that relative high expression of GSDMB, but no other GSDM genes, in breast tumours is associated with poor survival in unselected breast cancer cases." (PMID 27462779, 2016). "Here we demonstrate for the first time that high levels of GSDMB gene, but not the other GSDM members, are associated to poor prognosis (in terms of disease-free and metastasis-free survival) in human breast carcinomas." (PMID 24675552, 2014). "Furthermore, they also documented that both GSDMB-1 and GSDMB-2 could enhance breast cancer cell metastasis in a specific signaling pathway." (PMID 36823153, 2023). "Moreover, GSDMB overexpression promotes cell motility, invasion, and metastasis in breast cancer cell lines, but it does not affect cell proliferation." (PMID 36163066, 2022). "Moreover, GSDMB gene is frequently co-amplified with ERBB2/HER2 oncogene in breast and gastro-esophageal carcinomas, and in HER2+ breast cancers GSDMB upregulation promotes tumor aggressiveness and resistance to anti-HER2 therapies." (PMID 35281099, 2022). "Moreover, confirming our in vitro and/or in vivo data in human breast cancer cell lines and biopsies GSDMB levels did not produce a clear effect on tumor weight or proliferation in our murine models." (PMID 35281099, 2022). "Moreover, high levels of GSDMB decrease sensitivity to trastuzumab in vitro in HCC1954 and SKBR3 cells, and its expression increases during the acquisition of trastuzumab resistance in HER2 + breast cancer PDX models." (PMID 36163066, 2022). "However, unlike human HER2 breast carcinomas and xenografted MCF7 cells, GSDMB upregulation did not significantly associate with increased metastatic potential." (PMID 35281099, 2022). "Consistent with the GSDMB pro-tumor functions in human HER2 carcinomas, our two novel breast cancer models (R26-GB2/MMTV-NEU and R26-GB2/MMTV-PyMT) proved that GSDMB2 expression significantly augments breast cancer formation only in the context of HER2-driven tumorigenesis." (PMID 35281099, 2022). "However, the possibility that GSDMB/C promote breast cancer through pyroptosis-independent mechanisms is not ruled out." (PMID 33406603, 2021). "It was determined that the expression of GSDMB, which could be upregulated by interferon and mediated by pyroptosis in target cells, was related to the response to HER2-targeted therapy and prognosis in breast cancer." (PMID 34368222, 2021). "GSDMB is a member of the gasdermin (GSDM) family that consists of four genes, GSDMA, GSDMB, GSDMC and GSDMD, and is expressed in proliferating cells of normal epithelium and also in many types of cancer, including esophageal, gastric, liver, colon, uterine cervix and breast cancers." (PMID 26016667, 2015). "Thus, GSDMB can promote migration, adhesion and proliferation, through FAK phosphorylation changes mediated by PDGF-A, during gut epithelial barrier repair/restitution, while GSDMB effects on breast cancer invasion/metastasis and tumor growth depend on the cellular and in vivo contexts." (PMID 36163066, 2022). "Although GSDMA and GSDMB are located at the same human chromosomal region (17q21), unlike GSDMA, GSDMB is markedly over-expressed in breast cancer and acts as an oncogene." (PMID 36823153, 2023). "However, treatment with 5-aza-2’-deoxycytidine (5-aza-dC), a DNA methyltransferase inhibitor, could upregulate the expression of GSDMA but not GSDMB in the MCF7 cell, indicating that GSDMA expression is mediated by DNA methylation in breast cancer." (PMID 36823153, 2023).
inflammatory bowel disease (27 papers, 2015 to 2025). A spectrum of small and large bowel inflammatory diseases of unknown etiology. "Subsequent GWAS studies have also revealed associations between GSDMB and various inflammatory and immune-related diseases, including inflammatory bowel disease (IBD), chronic rhinosinusitis, primary biliary cirrhosis, and cervical cancer, among others." (PMID 40452932, 2025). "Human GSDMB polymorphisms are strongly associated with autoimmune diseases including inflammatory bowel disease (IBD) and asthma." (PMID 36189207, 2022). "In inflammatory bowel disease patients, GSDMB levels are increased, and caspase-1 cleaves GSDMB to trigger epithelial cell pyroptosis." (PMID 37500614, 2023). "A recent study focussing on the inflammatory bowel disease (IBD) role of GSDMB showed that GSDMB is able to regulate epithelial cell proliferation and migration, enhancing the repair process independent of pyroptosis." (PMID 37266429, 2023). "Gasdermin B (GSDMB) is highly expressed in inflammatory bowel disease and contributes to the progression of inflammation by disrupting epithelial barrier function and promoting the development of ferroptosis." (PMID 35958626, 2022). "The expression of GSDMB in the intestinal mucosal epithelium may provide broad-spectrum defense against inflammatory bowel disease (IBD), CRC, and intestinal infections." (PMID 38304430, 2024). "Additionally, GSDMB expression is increased in CRC and associated with inflammatory bowel disease (IBD) susceptibility." (PMID 39062587, 2024). "The results demonstrate that GSDMB interacted protein was significantly involved in cytokine–cytokine receptor interaction, sphingolipid metabolism, inflammatory bowel disease (IBD), and several immune pathways such as IL18/33 production, IFN-γ production, and inflammatory response." (PMID 37064151, 2023). "Previous studies have shown that GSDMB-induced excessive pyroptosis might lead to autoimmune disorders, such as asthma and inflammatory bowel disease (IBD)." (PMID 35962439, 2022). "Another study suggested that GSDMB was involved in the progression of inflammatory bowel disease, which may explain some of the pathogenesis links between IBD and colon cancer." (PMID 36127676, 2022). "Of note, GSDMB single nucleotide polymorphisms are linked to increased susceptibility to inflammatory bowel disease (IBD); as such, it is possible that GSDMB may play a role in CRC pathogenesis by promoting chronic intestinal inflammation, such as that observed in IBD." (PMID 35111698, 2021). "In inflammatory bowel disease (IBD), GSDMB expression is upregulated to promote effective epithelial restitution and repair." (PMID 38711020, 2024). "A recent study reveal differential distribution of GSDMB among colonic epithelial cell subtypes, predominantly in colonocytes, crypt top colonocytes, and goblet cells, through the supervised analysis of a large-scale scRNA-seq dataset from health controls and inflammatory bowel disease patients." (PMID 36505474, 2022). "In this review, we discuss the impact of pyroptosis on inflammatory bowel disease (IBD), with a focus on the executive proteins of pyroptosis (GSDMB, GADMD, and GSDME) and IBD-related endogenous damage-associated molecular patterns (DAMPs) produced by pyroptosis." (PMID 35677444, 2022). "Non-pyroptosis-related function of GSDMB was reported in inflammatory bowel disease (IBD), through regulation of restoration of the intestinal lining." (PMID 38737375, 2024).
bladder cancer (21 papers, 2021 to 2026). "Based on Kaplan‒Meier (KM) curve analysis, they showed that GSDMB and caspase-6 are associated with better prognosis in bladder cancer." (PMID 36702978, 2023). "At present, the specific role and underlying mechanism of GSDMB in bladder cancer need to be further explored." (PMID 34326684, 2021). "In the following, the mechanism underlying the regulation of the glycolysis of bladder cancer cells by GSDMB was studied." (PMID 34326684, 2021). "GSDMB overexpression associates with advanced disease or poor prognosis in breast, oral and gastric cancer, and increases invasive and/or metastatic behavior in breast and bladder cancer cells." (PMID 35281099, 2022). "It has been reported that USP24 bound to Gasdermin B (GSDMB) via the activation of the STAT3 pathway promotes bladder cancer cell proliferation." (PMID 38140768, 2024). "GSDMB, a member of the gasdermin protein family participating in the provoking of pyroptosis, has been proven to promote the progression of bladder cancer by activating the signal transducer and activator of transcription 3 (STAT3)." (PMID 38695942, 2024). "Abnormally up-regulated GSDMB can also enhance the growth and invasive ability of bladder cancer cells." (PMID 35571063, 2022). "GSDMB is frequently expressed in cancer cells, consequently, significant correlations were indicated between expression levels of GSDMB and overall survival of patients with bladder carcinoma or skin cutaneous melanoma." (PMID 35795683, 2022). "When the expression level of GSDMB is abnormally upregulated, the growth and invasive ability of bladder cancer can be significantly enhanced." (PMID 36338999, 2022). "Compared with other GSDMs, remarkable GSDMB expression was observed in bladder cancer cells, based on which we divided 7 tumor samples into high and low PRGScore groups." (PMID 35479097, 2022). "In particular, GSDMB is frequently expressed (mRNA/protein) in esophageal, gastric, colon, liver, breast, cervical and bladder cancers." (PMID 35281099, 2022). "Given the critical role of GSDMB in bladder cancer, we investigated the mechanism by which GSDMB promotes the progression of bladder cancer." (PMID 34326684, 2021). "In summary, we demonstrated that aberrantly up-regulated GSDMB was responsible for enhancing the growth and invasion ability of bladder cancer cells." (PMID 34326684, 2021). "Functional assays such as MTT assay, Celigo fluorescent cell-counting assay, Annexin V-APC assay and xenografts were used to evaluate the biological role of GSDMB in bladder cancer." (PMID 34326684, 2021). "In this study, we showed that GSDMB was up-regulated in bladder cancer tissues compared with adjacent normal tissue." (PMID 34326684, 2021). "The cell cycle analysis also showed that the number of bladder cancer cells in the S phase decreased when GSDMB was knocked down, indicating slow cell division and proliferation." (PMID 34326684, 2021). "After revealing the important role of GSDMB in bladder cancer, we studied how GSDMB was regulated in bladder cancer for the targeted treatment of bladder cancer." (PMID 34326684, 2021). "It is worth noting that the mRNA expression level of GSDMB in bladder cancer tissues was higher than that in adjacent normal tissues according to the bioinformatics analysis of the TCGA data set (n =19, P = 1.98e-2)." (PMID 34326684, 2021). "In vitro cell proliferation assays showed that the growth activity of bladder cancer cells was significantly inhibited after GSDMB was knocked down." (PMID 34326684, 2021). "In this study, we systematically studied the clinical pathological and biological effects of GSDMB in bladder cancer." (PMID 34326684, 2021). "We also found that the apoptotic rate of bladder cancer cells in the GSDMB silencing group was significantly higher than that in the control group in both 5637 and T24 cancer cells, as analyzed by the Annexin V-APC assay." (PMID 34326684, 2021).
bladder cancer (continued). "GSDMB also promotes bladder carcinoma progression by activating the STAT3 pathway." (PMID 38711020, 2024). "Contrary, the interaction between ubiquitin-specific peptidase 24 (USP24) and GSDMB prevents the degradation of gasdermin B in bladder cancer, and this may be a potential therapeutic target in the future." (PMID 39766111, 2024). "USP24 interacts with GSDMB and acts as a deubiquitinating enzyme (Dub) to remove polyubiquitin chains from GSDMB,304 increasing the stability of GSDMB in bladder cancer and further promoting downstream phosphorylation of STAT3, which promotes bladder cancer cell proliferation." (PMID 38584157, 2024). "In addition, they confirmed that the interaction between USP24 and GSDMB can prevent degradation of GSDMB in bladder cancer cells." (PMID 36702978, 2023). "Notably, GSDMB is markedly overexpressed in bladder cancer and clear cell renal cell carcinoma, correlating with poor prognosis." (PMID 38066523, 2023). "However, the better prognosis of patients with high GSDMB expression seems to contradict previous studies finding that high expression of this gene in bladder cancer promotes tumor cell proliferation." (PMID 35571063, 2022). "In conclusion, USP24 stabilizes GSDMB to promote STAT3 phosphorylation in bladder cancer cells." (PMID 34326684, 2021). "We further showed that USP24 inhibitors could block this process via inducing GSDMB degradation in cancer cells, which provided a therapeutic strategy for inhibiting the GSDMB/STAT3 axis in bladder cancer." (PMID 34326684, 2021). "Furthermore, we used cryptotanshinone to inhibit the phosphorylation of Tyr 705 STAT3 in bladder cancer cells with knocking down or overexpressing GSDMB, resulting in constant protein and mRNA levels of HK2." (PMID 34326684, 2021). "Collectively, our data suggest that GSDMB can regulate the glycolysis of bladder cancer cells." (PMID 34326684, 2021). "Concluding, GSDMB promotes bladder cancer progression in cells and mice." (PMID 34326684, 2021). "The results of the in vivo experiments were also completely consistent with these results, and no statistical difference in the tumor mass or volume was detected between the two groups, which further demonstrated that GSDMB promoted the progression of bladder cancer by regulating STAT3." (PMID 34326684, 2021). "First, we explored the clinical biological effects of GSDMB in bladder cancer." (PMID 34326684, 2021). "Then, we showed that GSDMB promoted bladder cancer progression." (PMID 34326684, 2021). "Furthermore, we also demonstrated that USP24 interacted with GSDMB and prevented GSDMB from degradation in bladder cancer cells." (PMID 34326684, 2021). "In conclusion, GSDMB regulates IGFBP3 expression through the STAT3 pathway in bladder cancer." (PMID 34326684, 2021). "In addition to the in vitro experiments, we also employed the nude mice xenograft tumor model after inhibition of the expression of GSDMB to study the growth-promoting effect of GSDMB in bladder cancer in vivo." (PMID 34326684, 2021). "Therefore, the USP24/GSDMB/STAT3 axis may be a new targetable signaling pathway for bladder cancer treatment." (PMID 34326684, 2021). "The Univariate Cox regression analysis revealed that eight PRGs (PRKACA, GSDMB, CASP9, GSDMD, CASP6, CASP8, AIM2, and CASP1) were significantly correlated with the prognosis in bladder cancer." (PMID 36120583, 2022). "In bladder cancer, the USP24/GSDMB/STAT3 axis is reported to promote tumor proliferation and growth, where USP24 interacts and stabilizes GSDMB, which in turn binds to STAT3, increases its phosphorylation and activates STAT3 signaling." (PMID 35479097, 2022). "Here, our results indicated that USP24 bound to GSDMB to stabilize GSDMB, and subsequently activated the STAT3 pathway in bladder cancer cells." (PMID 34326684, 2021). "We found that GSDMB bound to and activated STAT3 to modulate the glucose metabolism and promote tumor growth in bladder cancer cells." (PMID 34326684, 2021).
bladder cancer (continued). "GSDMB, CLEC2D, APOL2, TNFRSF14, and GBP2 were selected as prognostic genes in bladder cancer patients." (PMID 34708131, 2021). "We proved that knocking down or inhibiting USP24 increased the polyubiquitination of GSDMB, but overexpressing USP24 decreased the polyubiquitination of GSDMB in bladder cancer cells." (PMID 34326684, 2021). "Consequently, stabilized GSDMB has been shown to modulate glucose metabolism by enhancing signal transducer and activator of transcription 3 (STAT3) phosphorylation in bladder cancer cells." (PMID 38066523, 2023). "We constructed a prognostic model based on Necroptosis subtype-related prognosis DEGS by lasso algorithm and multivariate COX analysis, which consists of 6 predictors (CERCAM POLR1H, KCNJ15, GSDMB, EHBP1, TRIM38), among which CERCAM is closely related to bladder cancer." (PMID 35478725, 2022). "Mass spectrometry of GSDMB indicated that GSDMB may interact with USP24, which was verified in bladder cancer cells through immunoprecipitation." (PMID 34326684, 2021). "Overexpressed GSDMB promoted cancer cell growth via interacting with STAT3 to elevate the phosphorylation level of STAT3, which increased the expression of HK2, LDNA, ENO2, and IGFBP3 to enhance the glycolysis of bladder cancer cells." (PMID 34326684, 2021). "Furthermore, we demonstrated that GSDMB interacted with STAT3 to increase the phosphorylation of STAT3 and modulate the glucose metabolism and promote tumor growth in bladder cancer cells." (PMID 34326684, 2021). "GSDMB could bind to intracellular STAT3 and activate the STAT3 signaling pathway in bladder cancer." (PMID 36338999, 2022). "The role of GSDMB in bladder cancer has not been studied to date." (PMID 34326684, 2021). "Furthermore, we showed that USP24 could stabilize GSDMB, and the USP24/GSDMB/STAT3 signaling axis provided some potential therapeutic targets for bladder cancer." (PMID 34326684, 2021). "Then, we showed that GSDMB could bind to STAT3 and activate STAT3 signaling in bladder cancer." (PMID 34326684, 2021). "Moreover, GSDMB modulated the glycolysis by up-regulating the expression of HK2 in bladder cancer cells, suggesting that GSDMB might be involved in regulating the glucose metabolism of bladder cancer cells through STAT3-related signaling pathways." (PMID 34326684, 2021). "Given that USP24 promoted the expression of the GSDMB protein levels rather than that of the mRNA levels in bladder cancer cells, we hypothesized that USP24 may regulate the stability of GSDMB through the ubiquitinated proteasome pathway." (PMID 34326684, 2021). "Although we genetically silenced USP24 to prove the stabilization of GSDMB by USP24, we could not rule out that USP9x or USP5 acted as deubiquitinases of GSDMB in bladder cancer." (PMID 34326684, 2021).